VTRNA1-2 (vault RNA 1-2)
Synonyms: hvg-2; HVG2; VR2; VAULTRC2
Gene: Gene (Ensembl biotype vault_RNA) on chromosome 5 (140,718,925 to 140,719,013, forward strand). Ensembl gene ENSG00000202111.
Homologues: Orthologues: chimpanzee Vault (100% identical), pig Vault (75% identical), guinea pig Vault (74% identical), rabbit Vault (71% identical), guinea pig Vault (70% identical), rabbit Vault (69% identical). Paralogues in human: VTRNA1-3 (87% identical), VTRNA1-1 (76% identical), VTRNA3-1P (73% identical), Vault (66% identical), Vault (58% identical), VTRNA2-2P (57% identical), Vault (57% identical).
Diseases named in the same sentence as VTRNA1-2 in open-access papers:
VTRNA1-2 is named in the same sentence as 5 diseases in open-access papers, as found by Europe PMC text mining. Sharing a sentence is not in itself a finding about the gene and the disease.
VTRNA1-2 shares sentences with these, for which no sentence is quoted: adenoma (1 paper); diabetes insipidus (1); hematological disorders (1); Hyponatremia (1); tumor (1).